REN (renin)
Diseases named in the same sentence as REN in open-access papers (continued):
Sharing a sentence is not in itself a finding about the gene and the disease.
heart failure (continued). "In addition, the renin–angiotensin–aldosterone system is activated as a compensatory mechanism in children with heart failure." (PMID 41155980, 2025). "In humans, increased renin-angiotensin system activation in advanced cardiac disease has been hypothesized to contribute to hypothermia in heart failure." (PMID 40632033, 2025). "An amelioration of constipation might also normalize hyperkalemia and give clinicians chances to up-titrate anti-heart failure medications such as renin–angiotensin–aldosterone system inhibitors." (PMID 39124567, 2024). "The volumetric and pressure variables involved—affected regardless of the cause of heart failure—are the promoters of sympathetic activation, renin–aldosterone axis activation, free radical production, inflammation, and overactivation." (PMID 39595155, 2024). "Renin–angiotensin–aldosterone system inhibitors (RAASis) have been shown to reduce the risk of kidney failure and all-cause mortality in patients with chronic kidney disease (CKD) and of cardiovascular morbidity in patients with CKD or heart failure (HF)." (PMID 38253386, 2024). "Furthermore, AR and MR both end up in a decreased forward cardiac output (AR initially increases systolic volume but not organ perfusion), resulting in increased activation of the renin–angiotensin–aldosterone system and worsening heart failure." (PMID 39458178, 2024). "Second, heart failure may activate sympathetic nervous system and increase the tone of renin-angiotensin-aldosterone system." (PMID 38879473, 2024). "Decreased cardiac output in heart failure activates neurohormonal responses (namely, the renin–angiotensin–aldosterone and the sympathetic nervous systems) to maintain adequate cardiac function; however, this also leads to decreased cerebral perfusion, including perfusion to the eye." (PMID 39408001, 2024). "Clinical evidence suggests that sacubitril/valsartan is superior to conventional renin-angiotensin-aldosterone inhibitor therapy for patients with reduced ejection fraction heart failure who can tolerate angiotensin-converting enzyme inhibitors or angiotensin II receptor blockers." (PMID 37057101, 2023). "The pathophysiology of hyponatremia in patients with heart failure is complex, including numerous mechanisms: increased activity of the sympathetic nervous system and the renin–angiotensin–aldosterone system, high levels of arginine vasopressin and diuretic use." (PMID 36675801, 2023). "Dexrazoxane and heart failure medications (i.e., beta blockers and drugs targeting the renin–angiotensin system) are prescribed for the primary prevention of cancer therapy-related cardiotoxicity and for the management of cardiac dysfunction and symptoms if they arise during chemotherapy." (PMID 37174712, 2023). "For example, β-adrenoreceptor blockers, renin-angiotensin-aldosterone system blockers, and angiotensin receptor-neprilysin inhibitors are documented therapies considered for heart failure with reduced ejection fraction; however, other forms of heart failure require further investigations." (PMID 37706170, 2023). "In addition, histamine or tryptase, which act as vasodilators and pro-fibrotic factors secreted by mast cells, as well as renin can promote heart failure." (PMID 36511224, 2023). "Various pharmacotherapeutic agents conventionally used in the treatment of heart failure have been explored in randomised-controlled trials for the prevention of cardiac dysfunction, including inhibitors of the renin–angiotensin–aldosterone system and beta-blockers." (PMID 36672461, 2023). "Interestingly, during our review, we found that a systemic neurohumoral system (renin-angiotensin system), which plays a key role in homeostasis and heart remodeling during heart failure, operated autonomously in the Ca Pancreas milieu." (PMID 37623681, 2023).
heart failure (continued). "Prognostic effect of discontinuing renin–angiotensin–aldosterone-system-inhibitor (RAASi) for patients with heart failure (HF) after acute myocardial infarction (AMI) whose left ventricular (LV) systolic function was restored during follow-up is unknown." (PMID 36864119, 2023). "Aldosterone represents an important target of heart failure therapy and may be a valuable indicator of the renin-angiotensin-aldosterone system activity." (PMID 37670293, 2023). "UA Tech Launch, along with the authors, have filed USA patents application related to the methods of personalized treatment for cardiomyopathy and heart failure and other related diseases by measuring renin activity, pro-renin and (pro)renin receptor levels in blood (Pub." (PMID 36009420, 2022). "The presence of a central renin–angiotensin system means that locally produced angiotensin in the brain may also play a key role in autonomic dysfunction seen in heart failure." (PMID 35309046, 2022). "In heart failure, the renin-angiotensin system is activated along with an increase in the release of endothelin (ET-1) and cytokines; this complex association of neurohumoral factor cross-talk is thought to modify the pathogenesis of heart failure along with cardiac sympathetic activation." (PMID 36160916, 2022). "When abdominal aortic constriction is used, the renal blood flow is significantly reduced after abdominal aortic constriction in rats, which activates the renin-angiotensin-aldosterone system and brings about sodium and water retention in the body, aggravating the degree of heart failure." (PMID 36277986, 2022). "Activation of the renin–angiotensin system plays an active role in the remodelling of the heart and in fluid and electrolyte imbalance which are compensatory initially but eventually leads to worsening of heart failure." (PMID 35309046, 2022). "In heart failure, a combination of contributors, such as low cardiac output, activation of the renin-angiotensin-aldosterone system, and natriuretic peptide axes, and the sympatho-sympathetic reflex lead to tissue injury mainly through hypoperfusion and/ or congestion." (PMID 35887892, 2022). "Second, the renin‐angiotensin‐aldosterone system can be activated during IR to promote the reabsorption of sodium and water, which facilitates ventricular remodeling and leads to the occurrence of heart failure." (PMID 35770315, 2022). "Recent studies have repeatedly confirmed that the first and so far the only angiotensin receptor–neprilysin inhibitor (ARNI) sacubitril/valsartan can reduce blood pressure more effectively than renin–angiotensin system inhibitors and improve the prognosis of heart failure in patients with CKD." (PMID 35928297, 2022). "Some drugs (like renin–angiotensin–aldosterone system inhibitors) have been shown to reduce extracellular matrix deposition, but no primarily anti-fibrotic medications are currently used to treat patients with heart failure (HF)." (PMID 34671871, 2022). "Thus, there exists an inter-relationship between the renin–angiotensin system and sympathetic nerve activation in heart failure." (PMID 35309046, 2022). "Although the trial data cover a period before the routine use of cardiac resynchronisation therapy, neprilysin inhibition, and more recently gliflozins, the evidence base for all of these heart failure therapies is based on pre-existing renin-angiotensin and β1 adrenoreceptor blockade." (PMID 34474011, 2021). "Finally, the design of the CACP program was vague: there were no expectations to improve evidence-based therapies (e.g., to reach blood pressure targets, or ensure patients with heart failure were receiving a renin-angiotensin system inhibitor)." (PMID 34484483, 2021). "Furthermore, it leads to renin secretion by cells of the juxtaglomerular apparatus, which results in sodium retention and increased vascular congestion, with worsening heart failure." (PMID 34827580, 2021).
heart failure (continued). "In the worsening renal function group, there were higher occurrence rate of heart failure and severe coronary artery stenosis, lower rate of percutaneous coronary intervention, lower medication rate of renin-angiotensin blocker, lower plasma albumin, magnesium and hemoglobulin level." (PMID 34606471, 2021). "In the elderly coronary artery disease patients who had renal insufficiency, antiplatelet agents and statin have no adverse effects on renal function; lower medication rate of renin-angiotensin blocker was found in patients with either worsening renal function or heart failure." (PMID 34606471, 2021). "Progressive heart failure is associated with increased renin expression, but only mildly affected renal function without inducing structural injury." (PMID 34211391, 2021). "SZC may be a promising therapeutic tool to improve hyperkalemia, allowing up-titration of renin–angiotensin–aldosterone system inhibitors and facilitating cardiac reverse remodeling in patients with heart failure with LVEF <50% and hyperkalemia." (PMID 34884224, 2021). "Loop diuretics are frequently prescribed to patients with heart failure and reduced ejection fraction (HFrEF) for the treatment of congestion; however, they might hamper uptitration of inhibitors of the renin–angiotensin system." (PMID 32002631, 2020). "In this study, most patients were treated with β-blockers and renin-angiotensin-related drugs that have shown efficacy in heart failure, and it might be difficult to show the additional effect." (PMID 33066113, 2020). "We developed a novel murine heart failure model (triple‐tg) by cross‐breeding calsequestrin transgenic mice with human renin and human angiotensinogen double‐transgenic mice and investigated the cardioprotective effect of imarikiren at clinically relevant doses." (PMID 32056390, 2020). "At present, excessive activation of the neurohumoral endocrine system (Sympathetic nervous system and Renin-angiotensin system) and its consequent progressive ventricular remodeling are the most recognized mechanisms leading to the development of heart failure." (PMID 32498720, 2020). "Triple‐tg mice treated with 10 mg·kg−1 of TAK‐272 (imarikiren/SCO‐272), an orally active direct renin inhibitor, exhibited improvements in heart failure phenotypes, such as cardiac hypertrophy and survival rate; however, a dose of 300 mg·kg−1 was required to improve symptoms in CSQ‐tg mice." (PMID 32056390, 2020). "Neuroendocrine imbalance, with increased activity of the renin-angiotensin-aldosterone and sympathetic systems and diminished activity of the natriuretic peptides, has a major role in the transition of cardiac hypertrophy to heart failure." (PMID 33055420, 2020). "With regard to cardiovascular mortality, previous reports discussed that neurohumoral activation such as that of the renin angiotensin aldosterone system and sympathetic nervous activation exacerbates cardiac function, leading to poor prognosis in heart failure patients." (PMID 32817643, 2020). "This suggested that targeted therapy against LV remodeling in the form of beta-blockade (as used in heart failure) or renin-angiotensin blockade may be beneficial in LF AS to reduce harmful LV remodeling." (PMID 32493908, 2020). "H2S might protect the heart during heart failure by suppressing local renin levels through inhibition of MC infiltration and renin degranulation." (PMID 33239034, 2020). "In addition, we discuss the relevant molecular mechanisms that suggest BNP is protective against chronic kidney diseases and heart failure, especially in terms of the counterparts of the renin-angiotensin-aldosterone system (RAAS)." (PMID 31336656, 2019). "Here, we review the role of active renin, a crucial, upstream enzymatic regulator of the RAAS, as a prognostic and diagnostic plasma biomarker of heart failure with reduced ejection fraction (HFrEF) progression; we also discuss its potential as a pharmacological bio-target in HF therapy." (PMID 31261774, 2019).
heart failure (continued). "Regardless of the cause, symptomatic heart failure (HF) with reduced ejection fraction is characterized by pathological activation of the renin–angiotensin–aldosterone system (RAAS) with sodium retention and extracellular fluid expansion (edema)." (PMID 31261774, 2019). "This observational study is hypothesis generating and suggests that treatment of patients with heart failure and hyponatremia should perhaps be focused more on renin-angiotensin-aldosterone system reduction in certain racial groups, yet less in others." (PMID 31216316, 2019). "Heart failure (HF) patients frequently have elevated plasma renin activity." (PMID 31404946, 2019). "Renin-angiotensin-aldosterone system blockers may be considered during the period when regional wall motion abnormality is present in patients with heart failure with reduced EF." (PMID 31103033, 2019). "Therefore, SNT has potential benefits of improving cardiac function by inhibiting the excessive activation of Renin-Angiotensin-Aldosterone system in heart failure after myocardial infarction in rats." (PMID 30050591, 2018). "However, the effect of SNT in Renin-Angiotensin-Aldosterone system (RAAS) of heart failure after myocardial infarction in rats remains uncertain." (PMID 30050591, 2018). "Patients with heart failure and a reduced ejection fraction were more likely treated with drugs acting on the renin-angiotensin-aldosterone system and with beta-blockers as compared with patients with a preserved ejection fraction (p<0.01), while diuretics prescription was similar among subgroups." (PMID 29920539, 2018). "Future clinical trials of RAAS inhibition, especially renin inhibition, may continue to improve the heart failure patients’ outcomes but they should also be preceded with caution so as to avoid potential adverse events on the patients." (PMID 29152151, 2017). "First, hyponatremia is known to be related to higher mortality in patients with diseases activating the renin-angiotensin system and increasing vasopressin secretion, such as heart failure, liver cirrhosis, pulmonary embolism, pulmonary hypertension, pneumonia, and myocardial infarction." (PMID 29166900, 2017). "Blocking the renin-angiotensin-aldosterone system in ST-elevation myocardial infarction (STEMI) patients prevents heart failure and recurrent thrombosis in particular by the use of angiotensin-converting-enzyme (ACE) inhibitors if there are no contraindications to their use." (PMID 27064499, 2016). "We also observe increased plasma renin levels and activity, and higher circulating levels of angiotensin II in the TGR which can be both caused by renal sympathetic stimulation and by renal hypoperfusion during heart failure." (PMID 27496871, 2016). "Since reduced blood volume through increased water excretion may enhance renin secretion and upregulate the renin-angiotensin-aldosterone system (RAAS), loss-of-function of ClC-K/barttin channels might increase the risk of heart failure." (PMID 25339907, 2014). "Elevated levels of CRP have been observed in patients with HF, and activation of the immune response may play a role in heart failure through modifications in the renin-angiotensin-aldosterone and sympathetic systems." (PMID 24885051, 2014). "We investigated whether cyclooxygenase-2 (COX-2) inhibition in the PVN attenuates the activities of sympathetic nervous system (SNS) and renin-angiotensin system (RAS) in rats with adriamycin-induced heart failure." (PMID 23152801, 2012). "Of note, we preferred to use the RenTgKC model instead of the RenTgMK one, another variant of the RenTg mice, because of the lower expression of the renin transgene RenTgKC mice don’t die rapidly from heart failure and they can live long enough to develop renal disease." (PMID 23300650, 2012).
heart failure (continued). "Similarly, in the heart, beyond its haemodynamic effects, the ability of angiotensin II to induce TGF-ß expression is thought to be a major contributor to the beneficial effects of renin-angiotensin system (RAS) blockade in heart failure." (PMID 20209052, 2010). "In fact, apelin signaling may augment inhibition of the renin-angiotensin system, which is known to exacerbate heart failure when left unchecked." (PMID 18648539, 2008). "The core issue in heart failure is the reduced cardiac output, leading to hemodynamic disturbances and triggering compensatory mechanisms such as the Frank-Starling mechanism, activation of the sympathetic nervous system, and the renin-angiotensin-aldosterone system (RAAS)." (PMID 40771762, 2025). "Clinical and Biomarker Profile: Several biomarkers reflect renin–angiotensin–aldosterone system (RAAS) activation, including elevated plasma renin activity (PRA) and total renin levels, which have been linked to a poor diuretic response in heart failure patients." (PMID 40648765, 2025). "Lastly, these patients at increased risk might be eligible for preventive treatment, with either classic heart-failure treatment, such as beta-blockade or inhibition of the renin-angiotensin-aldosterone axis, or with the only FDA- and EMA- approved, but expensive, preventive drug dexrazoxane." (PMID 38689299, 2024). "Heart failure is believed to develop because of decreased effective hepatic perfusion and increased oxygen demand, coupled with reduced systemic vascular resistance, which stimulates the sympathetic nervous system and renin-angiotensin-aldosterone system, culminating in HOCF." (PMID 39759662, 2024). "A pre-existing, increased inflammatory profile along with the compensatory chronic activation of the sympathetic nervous system and the renin–angiotensin–aldosterone system may be responsible for the development of postoperative vasoplegia in patients with heart failure." (PMID 38202178, 2023). "During the onset of heart failure, the decreased cardiac output leads to insufficient renal blood perfusion, and the increased sympathetic tension promotes renin secretion to activate the renin–angiotensin–aldosterone system (RAAS), further aggravating renal damage." (PMID 38007545, 2023). "Given the wide distribution of the renin–angiotensin system in the cardiovascular system and in the heart, it is not surprising that angiotensin-converting enzyme inhibitors and angiotensin receptor blockers have become key first line therapeutic interventions in heart failure." (PMID 35309046, 2022). "However, there is still a lack of research on the related mechanisms of m6A methylation in the neurohumoral and renin angiotensin aldosterone systems of heart failure, which may provide new ideas for research and new perspectives for treatment." (PMID 35811741, 2022). "Heart failure development might activate the sympathetic nervous system and the renin-angiotensin-aldosterone system, leading to constriction of glomerular afferent arterioles and decreased glomerular filtration rate and renal blood flow due to low cardiac output." (PMID 36440270, 2022). "Symptomatic anemia overlaps with heart failure symptoms, and hemoglobin less than 7 g/dL may directly lead to heart failure in a mechanism that expands extracellular plasma volumes from increased sympathetic and renin-angiotensin activity." (PMID 34794458, 2021). "Those caring for people with heart failure must be cognisant that early increases in creatinine with SGLT2i are transient and be reassured that in the long-term the less rapid decline in renal function in patients receiving SGLT2i will allow more complete renin-angiotensin system blockade." (PMID 33653703, 2021).